BRCA1 (BRCA1 DNA repair associated)
Diseases named in the same sentence as BRCA1 in open-access papers (continued):
Sharing a sentence is not in itself a finding about the gene and the disease.
ovarian carcinoma (continued). "Although the estimated cumulative incidence of ovarian cancer by the age of 70 is 40% (95% CI 35–46%) for BRCA1 and 18% (95% CI 13–23%) for BRCA2 mutation carriers, the precise risk estimates vary according to the population under study, ascertainment method and applied statistical technique." (PMID 27914478, 2016). "Furthermore, a biological rationale driven (mutations in BRCA1/2) genomic instability score has been developed by integrating somatic mutations and copy number changes reported in the TCGA of 325 ovarian cancers." (PMID 27884198, 2016). "Therefore, we intend to enroll 60 BRCA1/2 mutation carriers in a pilot feasibility study (Lifestyle Intervention Study in Women with Hereditary Breast and Ovarian Cancer (LIBRE) pilot)." (PMID 28031860, 2016). "Interestingly, higher levels of miR-9 have been associated with a better outcome in ovarian cancer, where it was shown to directly target BRCA1." (PMID 27447934, 2016). "In addition, the rate of recurrence was reportedly lower in patients with BRCA1/2 mutations in triple-negative breast cancer patients, and prognosis was poor when expression level of BRCA1 was high in sporadic epithelial ovarian cancer patients." (PMID 27385216, 2016). "BRCA1 mutations predispose women to breast and ovarian cancers." (PMID 26973813, 2016). "BRCA1 protein is the most mutated gene in hereditary breast and ovarian cancers." (PMID 27277344, 2016). "Since currently available PARG inhibitors are not satisfying so far, questioned either for their specificity or for their cell permeability, we evaluated the impact of PARG depletion by siRNA on cell survival of several breast and ovarian cancer cell lines either proficient or deficient in BRCA1." (PMID 27375368, 2016). "The ovarian cancer association at 9p22.2 may be mediated by different variants in BRCA1 mutation carriers and in the general population." (PMID 27463617, 2016). "We collected whole fallopian tubes from 11 patients (BRCA1/2 mutation positive or with a family history of breast or ovarian cancer) who underwent RRSO and performed extensive sectioning (∼3000 slides) to detect SOC precursor lesions under the supervision of a pathologist (L.R.)." (PMID 27588493, 2016). "Since the majority of both BRCA1 and BRCA2 ovarian cancer associated cancer tumors are high-grade serous to increase the power of the association analyses, a meta-analysis combining HRs for the association of variants with ovarian cancer risk in BRCA1 and BRCA2 was conducted." (PMID 27463617, 2016). "Unfortunately, data on the frequency of BRCA1/2 germline mutations in Taiwanese patients with ovarian cancer are scarce, with the prevalence of somatic mutations being unknown." (PMID 27907908, 2016). "The results may also help to deepen our understanding of the biology of ovarian cancer development in BRCA1 and BRCA2 mutation carriers, potentially leading to the development of more effective and personalized treatments." (PMID 27463617, 2016). "The identification of BRCA1/2 somatic mutations may have implications for guiding therapeutic decisions in patients with ovarian cancer." (PMID 27907908, 2016). "In BRCA1 mutation carriers, one independent set of eight highly correlated (r2>0.8) SNPs could not be excluded as being potentially causal for the reported association with ovarian cancer, designated the "BRCA1 peak"." (PMID 27463617, 2016). "Additional work then demonstrated that, similar to breast and ovarian cancers harboring BRCA1/2 mutations, Ewing’s sarcomas may also have defects in DNA repair mechanisms, rendering them sensitive to PARP inhibition." (PMID 27336789, 2016). "BRCA1 mutation carriers face a high lifetime risk of developing both breast and ovarian cancer." (PMID 27534398, 2016). "Moreover, a BRCA1 variant with a single nucleotide substitution (Ser1164Ile) has been detected in women with family history of breast and/or ovary cancer." (PMID 26745677, 2016).
ovarian carcinoma (continued). "Manual curation uncovered several well-established disease causing mutations in this cohort without apparent Mendelian disease, including a 19-bp insertion-deletion variant in BRCA1 that has been previously implicated in hereditary breast and ovarian cancer, prompting prophylactic surgery." (PMID 26448358, 2015). "Although targeted screening for specific BRCA1 mutations can be offered to all Polish breast or ovarian cancer patients, NGS-based testing is justified in patients with breast or ovarian cancer likely related to BRCA1/2 who test negative for the selected BRCA1/2 pathogenic mutations." (PMID 25948282, 2015). "The absence of reliable methods for early detection and the poor prognosis associated with advanced ovarian cancer have supported the recommendation of bilateral risk reduction salpingo-oophorectomy (RRSO) after completion of childbearing in women with BRCA1 or BRCA2 mutation." (PMID 26669313, 2015). "Besides the breast and ovarian cancer patients, some solid tumors such as prostate, lung, endometrial, pancreatic and colon cancer are also associated with BRCA1/2 mutations." (PMID 26490766, 2015). "Interest is alsoincreasing in expanding testing for somatic mutations in ovarian cancer,particularly for genes such as BRCA1 and BRCA2, wherebymutations may allow more patients to benefit from targeted agents, includingpoly(ADP-ribose) polymerase inhibitors." (PMID 26669451, 2015). "In addition, in agreement with previous reports, we have demonstrated that low-expression of BRCA1 is associated with poor survival of ovarian carcinomas." (PMID 25823848, 2015). "In addition, DBC1 expression was significantly associated with BRCA1 expression and their expressions were related with resistance to platinum-based chemotherapy and poor prognosis of ovarian carcinoma patients." (PMID 25823848, 2015). "BRCA2 and BRCA1 germline mutations were identified in patients 4453 and 4485, respectively, as a consequence of genetic testing in hereditary cancer clinics due to their breast and ovarian cancer family history (see Figure supplemental S1 for pedigree)." (PMID 26622941, 2015). "These agents demonstrate synthetic lethality with inherent or induced defects in homologous recombination repair (HR), such as loss of Breast Cancer 1 and 2 (BRCA1/2) protein function, and have recently been approved for use in advanced ovarian cancers with a “BRCAness” phenotype." (PMID 26336991, 2015). "Mutations in the BRCA1 gene constitute a high life-time risk of breast and ovarian cancer." (PMID 26052370, 2015). "In addition to germline mutations, at least another 2–8 % of ovarian cancers have somatic BRCA1 and BRCA2 mutations, so that up to 20 % of patients with ovarian cancer have a BRCA1 or BRCA2 deficiency triggered by a mutation." (PMID 26109557, 2015). "Blood samples taken in two GOG studies (GOG 218 and GOG 262) were subjected to genetic testing and showed a BRCA1/2 mutation in 13.7 % of the patients with ovarian carcinoma, as well as mutations in other genes, in particular BRIP1, PALB2, CHEK2, NBN, and ATM, in 5.6 % of the patients." (PMID 26109557, 2015). "Nevertheless, these women have up to an 80% risk of developing breast or ovarian cancer by age 70 compared to women carrying two wild-type copies of BRCA1, due to the appearance of additional deleterious mutations within the wild-type BRCA1 allele in their somatic breast cells." (PMID 26042146, 2015). "About 15% of ovarian cancer patients in Polish population carry germline mutation in BRCA1/2 genes." (PMID 25591549, 2015). "Moreover, the 9p22 rs3814113 SNP has been demonstrated to be a protective genetic factor of ovarian cancer for carriers of BRCA1 or BRCA2 mutations." (PMID 25173882, 2015). "Loss of BRCA1/2 is known to lead to a higher predisposition to human breast and ovarian cancers." (PMID 25635998, 2015).
ovarian carcinoma (continued). "By analyzing multidimensional datasets of ovarian cancer patients from the TCGA data portal, we identified three miRNAs (hsa-miR-146a, hsa-miR-148a and hsa-miR-545) that target BRCA1/2 and were associated with overall survival and progression-free survival in patients with wild-type BRCA1/2." (PMID 25537514, 2015). "Other »high risk« ovarian cancer genes may exist, although mutations in these genes are probably less common than BRCA1 and BRCA2." (PMID 25810703, 2015). "In order to assess the feasibility of offering genetic testing of women with ovarian cancer, it is important to determine the frequency of BRCA1 and BRCA2 mutation carriers in populations where genetic testing is available as the prevalence may vary." (PMID 25884701, 2015). "While the general population lifetime risk of ovarian cancer is 1.4 %, women at high-risk of developing the disease due to their inheritance of a germline BRCA1 and BRCA2 mutation have an average cumulative risk of between 40 % to 75 % and 8 % to 34 %, respectively." (PMID 27231565, 2015). "BRCA1/2 mutations in here presented ovarian cancer patients." (PMID 25036526, 2014). "Characteristics of studies of patients with BRCA1/2 mutated ovarian cancer." (PMID 24788697, 2014). "BRCA1/2 mutations are present in approximately 11 to 15% of unselected ovarian cancer patients." (PMID 25051360, 2014). "Breast and ovarian cancer share susceptibility genes such as BRCA1/2 and RAD51C, making it likely that they may share mechanisms underlying cancer risk." (PMID 25389105, 2014). "Notably, the expression levels of GR decreased markedly, along with hypermethylated promoter-mediated BRCA1 deficiency in ovarian cancer." (PMID 24629067, 2014). "We in this study investigated in women with various forms of ovarian cancer whether the presence of BRCA1/2 mutations resulted in enrichment of low FMR1 mutations, which would suggest interplay between these two genes, in establishing oncogenic risk." (PMID 25036526, 2014). "In addition, inherited BRCA1 germline mutation revealed a genetic susceptibility leading to high risk of breast and ovarian cancers." (PMID 25426449, 2014). "Similarly, frame-shift mutations in the BRCA1 gene can be reversed by secondary mutations in cisplatin-resistant ovarian cancers." (PMID 24624361, 2014). "Similarly, pharmacological inhibition of ATR using VE-821 induced greater sensitivity to veliparib in BRCA1-deficient ovarian cancer cell lines." (PMID 25124282, 2014). "This is the second study of BRCA1 mutations in ovarian cancer patients from Belarus." (PMID 24770866, 2014). "BRCA1/2 germline mutations are responsible for genetic predisposition and may increase the risk for breast and ovarian cancer." (PMID 24961674, 2014). "In addition, the prevalence of BRCA1 mutations were examined in 592 sporadic Greek ovarian cancer patients." (PMID 25051360, 2014). "Possibly, it may also be somehow engaged in differential response to CHT in patients with hereditary, BRCA1 mutation-linked ovarian cancer." (PMID 24478986, 2014). "Ovarian cancers with mutated BRCA1/2 genes are particularly sensitive to agents that cause DNA double strand breaks (DSBs) and DNA interstrand cross-links, such as platinum compounds and poly (ADP-ribose) polymerase (PARP) enzyme inhibitors, for example olaparib and iniparib." (PMID 25429431, 2014). "Taken together, the currently available data indicate that the BRCA1 p.Ser36Tyr variant could be considered as a variant that confers a moderate risk for breast/ovarian cancer." (PMID 24695549, 2014). "Mutations of BRCA1 are found in a high percentage of hereditary breast and ovarian cancers." (PMID 24704793, 2014). "A BRCA1 mutation was detected in 25 of the 158 (15.8 %) unselected ovarian cancer cases." (PMID 24770866, 2014). "Aberrant methylation of the gene promoter may also serve as an alternative explanation for the loss of heterozygosity associated with BRCA1 deficiency in ovarian carcinomas." (PMID 24821107, 2014).
ovarian carcinoma (continued). "It was shown that carriers of BRCA1/2 mutations have also increased levels of estrogen, which may trigger breast and ovarian cancers." (PMID 25429284, 2014). "Our previous results suggested that promoter hypomethylation, especially around the ETS1 and ETS2 motifs, may be involved in the up-regulation of PARP1 expression in BRCA1-mutated ovarian cancer." (PMID 24448423, 2014). "Moreover, the role of PARP inhibitors for chemoprevention for breast and ovarian cancer in BRCA1 and BRCA2 mutation carriers has been proposed." (PMID 24317580, 2014). "Other cancers, apart from breast and ovarian cancer, are also associated with BRCA1/2 mutations." (PMID 25593598, 2014). "Our findings have important implications for the subsequent counseling and management of p.Ser36Tyr carriers, since they have an increased risk over the general population for developing breast/ovarian cancer, although this risk is lower than that observed for pathogenic BRCA1 mutations." (PMID 24695549, 2014). "It has been hypothesized that ovarian cancer patients with BRCA1/2 mutation have improved survival because of the sensitivity to specific DNA-damaging agents, such as cisplatin and carboplatin." (PMID 25437005, 2014). "Notably, the ETS1 motif was the critical site for PARP1 transcription only in BRCA1-mutated ovarian cancer cells (Fig. 1Bi-Biv)." (PMID 24448423, 2014). "Combinational inhibitions of S6 phosphorylation and PARP might predict to be particularly effective in cancers with PARP inhibitor resistance and HR defects, such as BRCA1-deficient breast and ovarian cancers." (PMID 24831086, 2014). "To estimate the proportion of ovarian cancers in Belarus, which are dependent on BRCA1 Slavic founder mutations, we sought the presence of three most frequent mutations (BRCA1: 5382insC, C61G and, 4153delA) in 158 consecutive unselected cases of ovarian cancer." (PMID 24770866, 2014). "Moreover, mutations in BRCA1/2 genes due to several mechanisms, such as germline mutations, somatic mutations, and epigenetic silencing, are present in 33% of ovarian carcinoma samples." (PMID 25158060, 2014). "However, the most significant trend was primarily observed in cells originating from BRCA1-mutated ovarian cancer." (PMID 24448423, 2014). "In addition, BRCA1 mutation carriers have a 30-40% chance of developing ovarian cancer, while BRCA2 mutations also increase the risk of ovarian, pancreatic, prostate, and male breast cancer." (PMID 25011685, 2014). "Cells with BRCA1/2 mutation have an impaired ability to repair DSBs via HR, which is conservative, and potentially error-free, resulting in increased genomic instability and the predisposition to ovarian cancer." (PMID 25437005, 2014). "SNP285C reduces the binding strength between the Sp1 transcription factor and the MDM2 promoter, and is associated with a significantly reduced risk of spontaneous breast, endometrial and ovarian cancer as well as a reduced risk of ovarian cancer among BRCA1 mutation carriers." (PMID 25327560, 2014). "Interestingly, the activation effect due to the loss of BRCA1 was primarily observed in cells originating from ovarian cancer, while 293 T cells were insensitive to the overexpression or knockdown of BRCA1." (PMID 24321281, 2013). "BRCA1 inherited mutations predispose to high risk of breast and ovarian cancers." (PMID 23586058, 2013). "Similarly, based on the known ovarian cancer risk-modifying loci, the 5% of BRCA1 carriers at lowest risk have an estimated lifetime risk of developing ovarian cancer of 28% or lower, whereas the 5% at highest risk will have a risk of 63% or higher." (PMID 23544013, 2013). "Furthermore, investigations among 1,763 hereditary BC and ovarian cancer (OC) families have recently found that c.66_68delAG, c.5123C>A, c.1961delA, c.3770_3771delAG, and c.5152+5G>A mutations were in 45.2 % of BRCA1 mutation carriers." (PMID 24312913, 2013).
ovarian carcinoma (continued). "However, in those patients with a family history of ovarian cancer, the rate of BRCA1 mutations is 80 and 15% for BRCA2 mutations." (PMID 24098868, 2013). "In the present work, 256 unrelated high-risk probands with breast and/or ovarian cancer from families living in Asturias were analyzed for the presence of a BRCA1 or BRCA2 gene mutation from October 2007 to May 2012." (PMID 23683081, 2013). "Furthermore, modeling the influence of these modifiers on cumulative risk of breast and ovarian cancer in BRCA1 mutation carriers for the first time showed that a wide range of individual absolute risks of each cancer can be estimated." (PMID 23544013, 2013). "Thus, 17q21.31 is likely a novel susceptibility locus for ovarian cancer in BRCA1 mutation carriers." (PMID 23544013, 2013). "The breast and ovarian cancer susceptibility gene (BRCA1) encodes a tumor suppressor." (PMID 23855721, 2013). "BRCA1 deletions are known to predispose to breast/ovarian cancer." (PMID 23967248, 2013). "Most BRCA gene studies in ovarian cancer have centered around the differential chemosensitivity profile known as “BRCAness syndrome” in selected patients with inherited BRCA1 and BRCA2 mutations who are reported to show enhanced sensitivity to platinum-based anticancer drugs." (PMID 23289505, 2013). "Notably, the expression levels of EGFR were markedly increased (P < 0.05), along with a hypermethylated promoter-mediated BRCA1 deficiency in ovarian cancer (P < 0.05)." (PMID 24321281, 2013). "Furthermore, the mutations are located closer to the 5 ′end of the BRCA1 gene are at higher risk for ovarian cancer than those to the 3′ end." (PMID 23941236, 2013). "Of the mutator genes identified in our analysis of lung and ovarian cancer, BRCA1/2, PRKDC, and PPP2R2A gene in the region 8p21.2 belong to this category although the role of PPP2R2A in inducing chromosomal instability in ovarian cancer was previously unknown." (PMID 24330428, 2013). "However, compound heterozygosity for two BRCA1 mutations, one of them apparently hypomorphic, has been described in a single patient with short stature, microcephaly and early ovarian cancer." (PMID 24025454, 2013). "BRCA2, like BRCA1 is a gene that has been causally linked to both breast and ovarian cancer." (PMID 24244370, 2013). "BRCA1 is a well known tumor suppressor gene identified in the nineties and germline mutations in this gene confer increased susceptibility to developing breast and ovarian cancer." (PMID 24832651, 2013). "Three cohort studies have identified a risk reduction with prophylactic bilateral adnexectomy in women with germ line BRCA1 or 2 mutations by comparing the incidence of ovarian cancer in the control group to the incidence of primary peritoneal carcinoma in the prophylactic adnexectomy group." (PMID 23553196, 2013). "Similarly, seven loci are associated with ovarian cancer risk for BRCA1 mutation carriers: 9p22, 8q24, 3q25, 17q21, 19p13, 17q21.31 and 4q32.3." (PMID 23544013, 2013). "Approximately 15% of ovarian cancers (OCs) arise due to inherited BRCA1 or BRCA2 mutation." (PMID 23548133, 2013). "Finally, two pioneer studies using next-generation sequencing techniques reported an 18% prevalence in BRCA1 & BRCA2 (11.3% for BRCA1) mutations in ovarian cancer patients, while the Cancer Genome Atlas (TCGA) Research Network reported 14% (8.5% for BRCA1)." (PMID 23536787, 2013). "Interestingly, we observed that the knockdown of BRCA1 was an effective way to induce an increase of EGFR levels in SKOV3 and non-BRCA1-mutated ovarian cancer cells." (PMID 24321281, 2013).